IL17A (interleukin 17A)
Diseases named in the same sentence as IL17A in open-access papers (continued):
Sharing a sentence is not in itself a finding about the gene and the disease.
Candida infection (158 papers, 2011 to 2026). "Although patients with monogenic diseases with loss of IL-17 have increased risk for candidiasis, monoclonal antibodies against IL-17A seem to be relatively safe." (PMID 34539646, 2021). "The IL-17A and IL-6 cytokines are specifically induced in the patients after Candida infection, making them a potential target for diagnostic purposes." (PMID 34684298, 2021). "Patients with autoimmune polyglandular syndrome type 1 (APS-1) syndrome have neutralizing antibodies against IL-17A, IL-17F and/or IL-22, and have increased risk for candidiasis." (PMID 34539646, 2021). "At odds with IL-17A that controls fungal proliferation and infection, and whose blockage has been associated with fungal overgrowth and candidiasis, IL-17C is dispensable for immunity against candidiasis." (PMID 33244315, 2020). "Blocking IL-17A with secukinumab or ixekizumab may increase the risk of infections, specially involving respiratory airways (upper and lower), otitis, oral herpes, tinea pedis and candidiasis." (PMID 36619513, 2022). "Similarly, multiple patients with autoantibodies against TH-17 cytokines (comprising IL-17A, IL-17F, IL-22, IL-23) whose selective susceptibility to candidiasis strongly resembles inborn deficiencies with impaired production or response to IL-17 were described." (PMID 32419033, 2020). "Localized candida infections were reported in a low proportion of patients treated with ixekizumab, likely related to the function of IL-17A in defense against these pathogens." (PMID 39063970, 2024). "In oral and intestinal inflammation due to oral Candida infection, the Treg population has a multilayered protective role, one for IL-17A induction in CD4+ T cells and another for immunomodulation to prevent excessive inflammation." (PMID 36923589, 2023). "The risk of Candida infection was 4- to 10-fold higher with anti-IL-17A Abs than with TNF inhibitors, and the requirement for antifungal agents increased 2- to 16-fold after anti-IL17A Ab was started." (PMID 36430392, 2022). "Several studies have shown IL-17A to play an important role in the development of the inflammatory response and host defense against Candida infections." (PMID 34684298, 2021). "Collectively, these results showed that IL-1β/IL-1R signaling is required for promoting mTOR activation and IL-17A induction in Foxp3+ cells during Candida infection in oral mucosa." (PMID 33240286, 2020). "We next examined the role of Casz1 during oral Candida infection, a model in which IL-17A and Th17 cells are required for anti-fungal defense in the host." (PMID 29467767, 2018). "Candida infections are also a common adverse event observed upon anti-IL-17A or anti-IL-17RA-targeted therapies." (PMID 30127781, 2018). "As part of autoimmune processes, all patients have autoantibodies against at least one out of three IL-17 cytokines (IL-17A (41%), IL-17F (75%) and/or IL-22 (91%)), which are essential for host defense against mucocutaneous Candida infection." (PMID 29371502, 2018). "In contrast, intradermal acute Candida infection in mice induced Th17 cells that quickly lost IL-17A production." (PMID 28542595, 2017). "The IL-17A/IL-17R signaling axis has have been studied most extensively in the context of candidiasis." (PMID 29371568, 2017). "In summary, Th17 cells seem to be of great importance for the host protection against fungi, and their signature cytokine IL-17A was identified to be a promising biomarker for the identification of patients suffering from an invasive candidiasis." (PMID 28820494, 2017). "The cytokine IL-17 (IL-17A) and its receptor subunits, IL-17RA and IL-17RC, are required for protection to most forms of candidiasis." (PMID 25849644, 2015). "In naïve settings, the dominant source of IL-17A during a primary oral Candida infection in mice comes from γδ-T cells and nTh17 cells." (PMID 25849644, 2015).
Candida infection (continued). "Interesting patterns of induction of the IL-17 family by Candida infection were observed; IL-17A was dependent on NLRC4, NLRP3 and ASC whereas IL-17F was only dependent on NLRP3 with comparable induction seen in WT, NLRC4 and ASC deficient mice." (PMID 22174673, 2011). "Furthermore, multiple studies indicated the role of IL-17A in protection against C. albicans (an important cariogenic organism) and its regulation of antifungal immunity, IL-17A is crucial for combating candidiasis both at mucosal and systemic levels." (PMID 40321779, 2025). "Of note, current GRAPPA guidelines recommend against the use of IL-17A inhibitors in patients with comorbid IBD owing to the risk of exacerbation, and these therapies have also been associated with an increased risk of Candidiasis." (PMID 38773563, 2024). "Since the natural effect of antifungal immunity by IL-17A, long-term use of IL-17 inhibitors may lead to Candida infections." (PMID 37942312, 2023). "As a result, we suppose that IL-17A might induce the oral cells to secrete AMPs, which can synergistically interact with the combined drugs to combat against the dual Candida infections." (PMID 35195502, 2022). "CD3+/CD4+ Th17 cells are likely to be the primary sources of IL-17A during mucosal candidosis." (PMID 34209407, 2021). "For instance, IL-17A was shown to induce the production of occludin specifically in the gut, where it helps maintaining the intestinal barrier integrity, or favor the release of kallikrein 1 by renal epithelial cells, conferring protection against candidiasis." (PMID 30127781, 2018). "Indeed, Krause and colleagues were recently able to show that candidemic patients have significantly higher IL-17A plasma levels in comparison to non-candidemic patients, thus suggesting a potential role of IL-17A for the anticipation of invasive candidiasis." (PMID 28820494, 2017). "Candida infection, which could theoretically increase with IL-17A inhibition, was reported in three cases, with pooled adjusted incidence of candidiasis in secukinumab-treated patients across the two studies of 0.9 events per 100 patient-years of exposure." (PMID 28149838, 2017). "Although the importance of IL-17RA/RC was clear, IL-17RA is used by other ligands including IL-17C, leaving open the possibility that cytokines in addition to IL-17A might contribute to immunity to candidiasis." (PMID 25849644, 2015). "Of the other IL-17 family members, we considered that IL-17C and its receptor IL-17RE were the most likely to be important in candidiasis, given the similarity of the IL-17A- and IL-17C-induced downstream gene profiles and their common propensity to act at mucosal surfaces." (PMID 25849644, 2015). "Indeed, Il17c mRNA was strongly induced following Candida infection, in a manner similar to Il17a mRNA." (PMID 25849644, 2015). "Additionally, cytokines such as Interleukin-2 (IL-2), IL-6, IL-10, and Interleukin-17A (IL-17A) were significantly elevated in patients with bloodstream Candida infections compared to bacterial BSIs, demonstrating their capacity to differentiate between fungal and bacterial pathogens." (PMID 40137168, 2025). "Interestingly, SqP (with secondary Candida infection) had significantly lower numbers of IL-17A expressing cells (Dunn’s post hoc test: p = 0.044 for CHC vs. SqP), which might suggest higher immune tolerance to Candida in SqP." (PMID 34209407, 2021). "Whether bi-specific antibodies blocking both IL-17A and IL-17F have an increased risk of Candidiasis is not yet known." (PMID 30127781, 2018). "Notably, two (patients T24 and T31) showed remarkably high IL‐17A‐ and IL‐17F‐binding and had candidiasis; nevertheless, these antibodies cannot be a strong predisposing factor, as two other patients with CMC and five with intercurrent Candida infections tested negative against IL‐6." (PMID 27957331, 2016).
Candida infection (continued). "The most advanced vaccine currently developed against systemic candidiasis is based on Als3p and generates specific T cells that produce IFN-γ and IL-17A, both of which are required for a protective response." (PMID 39796100, 2024). "Mice lacking IL-17A showed delayed healing after C. albicans skin infections, and injections of exogenous IL-17A promote the faster healing of candidiasis." (PMID 33879639, 2021). "The pro-inflammatory cytokine, IL-17A, and its regulatory factors of EBI3 and IL-12A (which combine to form the anti-inflammatory cytokine IL-35) are likely to be highly relevant factors in combating Candida infection." (PMID 34209407, 2021). "Based on the limited discriminating competence between candidemia and bacteremia, IL-17A has to be considered a biomarker for blood stream infection rather than invasive Candida infection." (PMID 33535593, 2021). "In view of the limited ability to distinguish candidemia from bacteremia, IL-17A has to be considered as a biomarker for bloodstream infection rather than invasive Candida infections, as recently reported." (PMID 34684298, 2021). "Using a murine model of systemic candidiasis, we could confirm reduced generation of IFN-γ- and IL-17A-producing cells in ONX 0914 treated mice in vivo." (PMID 26776888, 2016). "To date, the source of IL-17A during systemic candidiasis is not well defined in mice or humans, but is thought to be innate." (PMID 25849644, 2015). "Although TLR-2 signaling promotes Treg proliferation during systemic candidiasis, IL-17A induction was not assessed in Tregs during the infection." (PMID 25790134, 2015). "Comparisons of IL-17A and IL-17F generally indicate that IL-17A is more potent than IL-17F in mediating immunity to candidiasis, though this issue is still not fully defined." (PMID 25849644, 2015). "As IL-17A plays an important role in mucosal immunity in general and protection against infections (namely by candida) in particular, it is not surprising that candida infections are a common adverse event of these drugs." (PMID 37283755, 2023). "In fact, we could not demonstrate significant differences in IL-17A values between patients with invasive Candida infection and S. aureus bacteremia." (PMID 33535593, 2021). "Following this, IL-17A may be valuable as a biomarker for either fungal or bacterial blood stream infection rather than solely for invasive Candida infection." (PMID 33535593, 2021). "However, human patients lacking the IL-17A receptor do not suffer from mycobacterial infections, whereas patients with mutations in RORC lack the Th1* subset able to produce both IFN-γ and IL-17 (patients do not produce IL-17 A and IL-17 F) and suffer from both Mycobacterium and Candida infections." (PMID 29270166, 2017). "Together, these data suggest that IL-23 might be the key Syk-dependent cytokine driver of DC-mediated resistance to candidiasis, consistent with the fact that addition of recombinant IL-23 and not recombinant IL-17A/F to purified NK cells induces GM-CSF production." (PMID 25033445, 2014).
uveitis (158 papers, 2009 to 2026). An inflammatory process affecting a part of or the entire uvea. "IL-17A secretion by CD4+ T cells have also been shown to be associated with active uveitis in patients with VKH or Behçet’s disease." (PMID 40433375, 2025). "We further studied the link between IL-17A polymorphisms with the risk of uveitis and the risk of a typical feature of JIA: TMJ arthritis." (PMID 39125893, 2024). "During uveitis, elevated levels of cytokines such as TNFα or IL-17A cause disruption of RPE barrier properties." (PMID 32101556, 2020). "Inhibition of IL-17A (secukinumab and ixekizumab) alone might increase the risk of uveitis, while simultaneous inhibition of IL-17A and IL-17F (bimekizumab) significantly reduced the risk." (PMID 40621455, 2025). "Inhibition of IL-17A alone might increase the risk of new-onset or recurrent uveitis, but simultaneous inhibition of IL-17A and IL-17F significantly reduced the risk of uveitis." (PMID 40621455, 2025). "However, this network meta-analysis demonstrates that anti-TNF mAb are associated with a lower incidence of uveitis compared to placebo and anti-IL17A." (PMID 34271991, 2021). "In fact, we did not observe differences in the cytokine profile between Caucasian and African patients (data not shown), which allows us to speculate that the observed increased levels of IFN-γ, TNF-α, and IL-17A may apply to uveitis associated with BD from any origin." (PMID 24994946, 2014). "In contrast to formerly tested anti-IL-17-antibodies with moderate therapeutic effect on uveitis this novel antibody targets both, IL-17A and -F and is thus expected to be more effective." (PMID 41142785, 2025). "A recent approved drug for axial spondyloarthritis, bimekizumab, a monoclonal antibody that selectively inhibits IL-17A and IL-17F, has showed a lower incidence rate of uveitis among patients randomized to this drug in a pooled analysis from phase 2b/3 trials." (PMID 40084348, 2025). "Localised cytokine expression demonstrates that uveal IL-23R+ IL-17A-producing cells are both necessary and sufficient to drive uveitis in response to IL-23." (PMID 40875563, 2025). "This change in microbiota composition reduces uveitis severity by increasing Treg cells in lymphoid tissues and the eye, reducing bacterial diversity and IL-17A+ T cells in the gut." (PMID 40005638, 2025). "In contrast, Bimekizumab, by simultaneously targeting both IL-17A and IL-17F, demonstrates superior uveitis prevention in clinical trials." (PMID 40621455, 2025). "Our data suggest that the aetiology-specific inflammatory mediators that are elevated in the disease entities associated with uveitis included in this study are IL-10 in IOL, RANTES and IFN-α2 in ARN, and IL-6, IL-17A, IL-22, and G-CSF in BE." (PMID 32066796, 2020). "The first indication of the central role of IL17 came from studies on human OT patients who showed strong ocular IL17A expression, in striking contrast to viral and other uveitis cases." (PMID 33382688, 2020). "The only anti-IL17 agent studied in the treatment of uveitis was secukinumab, a fully human monoclonal antibody that neutralized IL-17A." (PMID 33171664, 2020). "We have previously reported that Th2 and Th17 cell-related cytokines; specifically IL-4, IL-10, IL-17A, IL-22, IL-31and TNFα, are exclusively elevated in the vitreous fluid of PDR compared with that of ERM, MH, or uveitis associated with sarcoidosis." (PMID 28558009, 2017). "Several papers already reported BD patients with uveitis showed similar levels of IL-17A between active and inactive stage." (PMID 28377641, 2017). "IL-17A protein was furthermore found to be highly expressed by peripheral blood mononuclear cells (PBMCs) from uveitis patients." (PMID 22162626, 2011). "The evidence suggests that downregulation of IL-17A might be an important event to halt the intraocular inflammation and, therefore, it could be a marker of therapeutic response in the context of uveitis." (PMID 40433375, 2025).
uveitis (continued). "More recently, this inhibitory activity of IL-17A was explored in an autoimmne uveitis model (EAU)." (PMID 38639570, 2024). "This suggests that Müller glia may alter gene expression broadly in response to IFN-γ, while IL-17A may subtly shape the chemokine expression profile during uveitis." (PMID 39198470, 2024). "Elevated interleukin (IL)-6, IL-8, and IL-17A in serum samples of active uveitis suggest that uveitis may be an indicator of disease activity and systemic inflammation in AS." (PMID 35757729, 2022). "ROR-γt mRNA levels and frequencies of IL-17A+ Th17 cells are elevated in BD patients with uveitis." (PMID 33868228, 2021). "In RCTs assessing anti-TNF and anti-IL17A in axSpA, incident uveitis are rare events." (PMID 34271991, 2021). "In patients with uveitis, serum IL-17A levels were elevated during active disease." (PMID 34604268, 2021). "IL-17A, the product of T helper 17 cells is a major contributor to the onset of uveitis." (PMID 32101556, 2020). "Interestingly, a cross-reactive IL17A antibody has recently been reported and was used to assess FIP-associated uveitis." (PMID 31569783, 2019). "Similarly, another anti-TNFα therapy, infliximab, reduces IL-17A in ocular fluid from uveitis patients with Behcet’s disease." (PMID 24823369, 2014). "We showed that IFN-γ, IL-17A, TNF-α, and hsCRP are increased in active uveitis associated with BD." (PMID 24994946, 2014). "However, targeting IL-17A in the treatment of uveitis is ineffective, as IL-17A deficiency does not reduce the pathogenicity of Th17 cells in uveitis but rather increases the expression of GM-CSF and IL-17F." (PMID 39076973, 2024). "None of the studied IL-17A or IL-10 polymorphisms seemed to mediate the risk of uveitis." (PMID 39125893, 2024). "Despite implicated in the pathogenesis of uveitis, inhibiting IL-17A was not effective for uveitis." (PMID 34604268, 2021). "Similarly, IL-17A was increased in patients with active uveitis compared to healthy controls." (PMID 24994946, 2014). "The pathogenesis of uveitis involves elevated Notch1, DLL4, IL-17A, and RORγt, and decreased levels of miR-30b-5p." (PMID 40918405, 2025). "While TNFα is generally thought to participate in the pathogenesis of uveitis, and anti-TNF drugs are effective for panuveitis and posterior uveitis treatment, IL-17A and IL-17F are also reported to be involved in anterior uveitis progression." (PMID 37238999, 2023). "The levels of EGF, fractalkine, IL1-β, IL-17A, IL-1RA, IL-2, IL-23, IL-8, IP-10, TNF-α and IL-6 in patients with uveitis in their active phase were independent to their counterpart levels in plasma, the difference being statistically significant (p < 0.05)." (PMID 36498608, 2022). "Higher levels of IL-17A have been detected in the vitreous fluid of DMO patients, PDR patients, in AMD lesions and in the serum of uveitis patients." (PMID 34356895, 2021). "Incidence of uveitis was lower with anti-TNF mAb versus placebo (OR = 0.46; CI 95% [0.24; 0.90]) and versus anti-IL17A (OR = 0.34; CI 95% [0.12; 0.92]." (PMID 34271991, 2021). "According to the P-score, the ranking from the most to the least preventive treatment of uveitis flare was as follows: anti-TNF mAb, ETN, placebo, and anti-IL17A." (PMID 34271991, 2021). "Secondly, IL-17A critically contributes to the pathogenesis of DR, AMD and uveitis, all of which can lead to macular oedema." (PMID 34356895, 2021). "In conclusion, we have demonstrated that the aetiology-specific inflammatory mediators elevated in different types of uveitis include IFN-α2 in ARN and IL-6, IL-17A, and G-CSF in BE." (PMID 32066796, 2020). "Increased intracellular IL-10 and IL-17A and decreased intracellular IFNγ levels were found in CD4+ T-cells from active uveitis, 6 months after starting treatment, when the disease had clinically resolved." (PMID 29774027, 2018).